CLDN5 (claudin 5)
Diseases named in the same sentence as CLDN5 in open-access papers (continued):
Sharing a sentence is not in itself a finding about the gene and the disease.
infection (continued). "Upon flavividae infection, BBB and TJ are often disrupted: infection with West Nile virus and classic swine fever virus both lead to claudin-1 degradation and Japanese encephalitis virus infection induces the degradation of claudin-5." (PMID 34616388, 2021). "The results of the present study as well as previous studies suggest that Cdh5 and Cldn5 are major determinants of BBB deterioration during infection, while Wnt/β-catenin signaling may contribute to the maintenance of BBB integrity." (PMID 32509459, 2020). "No changes in protein content occurred at early time points, however, a trend for a decrease of ZO-1, Occludin, and Claudin-5, could be observed at 32 h of infection." (PMID 31191497, 2019). "With further in vivo and in vitro verification in response to infection, we demonstrated that meningitic E. coli-induced PDGF-BB negatively regulated the expression of TJ proteins including ZO-1, Occludin, and Claudin-5, enlarging endothelial permeability and causing BBB disruption." (PMID 31092253, 2019). "Claudin-5 could be used for the pathophysiologic evaluation of the blood-CSF barrier breakdown and tight junction disruption after infection with A. cantonensis." (PMID 23505411, 2013). "Our results indicate that resistin secreted by PAMs reduces claudin-5 and occludin expression in co-cultured PAECs and increases the permeability of monolayer PAECs, implying that resistin plays an important role in maintaining endothelial integrity during pathogen infection." (PMID 36694280, 2023). "On d 8 (peak infection), CQ30 birds exhibited a significantly greater abundance of CLDN1 and CLDN5 (p = 0.0016 and p = 0.0038, respectively) compared to NC and PC, as well as AMPK compared to all other treatments." (PMID 37630454, 2023). "Regarding infection with ZIKV-U stains, TJ proteins were downregulated in infected brains, achieving statistical significance only for claudin-5." (PMID 31620112, 2019). "A significant reduction in claudin-5 levels was observed in cells infected with ZIKV-PR and ZIKV-U throughout the infection time points analyzed." (PMID 31620112, 2019). "Reduction in levels of Cldn5 transcript in the spleens of all three inbred strains may be demonstrative of disrupted splenic architecture in the face of the massive haemophagocytosis in this organ in response to infection and/or the transformation of the spleen to erythropoietic function." (PMID 20844758, 2010). "In contrast, infection with the ΔK/R-ab mutant did not affect Claudin-5 expression compared to control larvae." (PMID 41310669, 2025). "Eta variant at MOI 1 also transiently induced an increase in tight and adherens junction expression at 2 dpi (median increase for TJP1: 33.5%; F11R: 38.3%; OCLN: 25.9%; CLDN5: 96.6% and CDH5: 74.5%) before expression levels returned to the uninfected condition ones after 6 days of infection." (PMID 37537664, 2023). "Interestingly, expression of OCLN was increased in hCMEC/D3s with infection, and we observed a tendency towards upregulation of TJP1 and CLDN5 together with downregulation of SNAI1 after 8 h of N. meningitidis infection." (PMID 36289516, 2022). "Additionally, blood-brain barrier integrity, as measured by the vascular tight junction protein claudin-5, was reduced by SARS-CoV-2 MA10 infection in all three strains." (PMID 36680154, 2022). "The transcript downregulation corresponded to a loss of tight junction complexes, as immunostaining revealed that occludin, claudin-5, and ZO-1 proteins were noticeably discontinuous or absent from cell-cell junctions following infection." (PMID 29104935, 2017). "Compared to mock infection, we did not observe any differences in claudin-5 expression in either the vehicle- or Efavirenz-treated group." (PMID 28008980, 2016). "The infection with EcoHIV did not alter the MFI values for claudin-5 and occludin; however, ZO-1 levels were diminished as compared to mock infection." (PMID 28008980, 2016).
infection (continued). "Moreover, junction molecules, namely, claudin-5, occludin, ZO-1, and VE-cadherin, which are essential proteins for maintaining the permeability of the BBB, were dramatically decreased in response to CV-A10 infection." (PMID 37577373, 2023). "Over the 24 hours after infection, claudin-5 could not be detected in lysosomes, and we detected no colocalization of poly-ubiquitin and claudin-5 by immunofluorescence (data not shown)." (PMID 23115643, 2012). "Notably, in zebrafish larvae immunolabeled for Zo-1, we again observed that Pg W83 infection led to a significant decrease in mean EGFP fluorescence intensity within cerebral vasculature compared to both control and ΔK/R-ab-infected larvae, similar to what was seen with claudin-5 staining." (PMID 41310669, 2025). "Unlike the invasion mechanisms of protozoans, during infection by the nematode A. cantonensis, an increase in Cav-1 expression in the brain and through the TLR4/MyD88 signaling pathway to activate MMP-9 leads to degradation of tight junction proteins (Zo-1 and claudin-5)." (PMID 38922036, 2024).
cancer (47 papers, 2012 to 2025). A tumor composed of atypical neoplastic, often pleomorphic cells that invade other tissues. "CLDN5 is implicated in the oncogenesis of diverse cancer types, highlighting its potential significance in cancer biology." (PMID 39869563, 2025). "According to the findings of the Kaplan-Meier analysis, increased CLDN5 expression was associated with a poor prognosis in four types of cancers, namely, COAD, GBM, KIRP, STAD, LUSC, and UVM." (PMID 37286335, 2023). "CLDN5 expression and immune infiltration were found to be strongly linked to various types of cancers." (PMID 37286335, 2023). "CLDN5 expression was also linked to MSI in 33 different cancers, including ACC, DLBC, ESCA, READ, STAD, and UCEC, with positive correlations for DLBC and negative correlations for STAD, READ, UCEC, and ACC." (PMID 37286335, 2023). "According to the current findings, CLDN5 has a strong association with stromal and immune scores, and CLDN5 expression is strongly correlated with the estimated score in most cancer types." (PMID 37286335, 2023). "The results implied that the major mutations in CLDN5 are frameshift, missense, and deletions in many sites of most cancers, indicating that mutations of CLDN5 are likely to be associated with cancers." (PMID 37286335, 2023). "Taken together, our results showed that induction of COX-2 and MMP1 in BC cancer cells was associated with loss of claudin-5 and VE-cadherin in the brain endothelial cells and increased trans-endothelial migration." (PMID 32645833, 2020). "CC Hela cells reduce tight junction-associated proteins ZO-1 and CLDN5 by activating the exosome-endoplasmic reticulum stress process, which in turn disrupts endothelial cell tight junctions and breaks through defenses leading to cancer metastasis." (PMID 39165926, 2024). "CLDN5 was found to be strongly associated with immune gene expression in a variety of cancers." (PMID 37286335, 2023). "In several cancers, lower CLDN5 expression was associated with a worse OS, DSS, DFI, or PFI." (PMID 37286335, 2023). "Endothelial cells that were associated with cancer cells displayed reduced claudin-5 in BrMs with a moderate-high degree of peritumoural oedema (oedema score 2–3); this relationship was absent in BrMs with absent or low peritumoural oedema (oedema score 0–1.5)." (PMID 36725935, 2023). "There was an association between claudin-5 expression and cancer grade and stage." (PMID 23685873, 2013). "Cancer-specific and overall survival was also associated with claudin-5 expression." (PMID 23685873, 2013). "CLDN5 expression levels differ significantly between cancer and normal tissues, and it has been confirmed in multiple studies." (PMID 39869563, 2025). "An observable trend in the expression of claudin-5 has emerged, revealing that, as cancer progresses, its expression increases, but its pattern changes from a linear thread-like form to a clumped and thickened one." (PMID 39858080, 2025). "In this study, we present the first comprehensive analysis of CLDN5 and pan-cancer, including prognosis, immune infiltration, methylation and mutation." (PMID 37286335, 2023). "Cox regression analysis of PFI indicated that CLDN5 expression influenced eight types of cancers, such as STAD, UVM, KIRP, COAD, THCA, UCEC, and PAAD." (PMID 37286335, 2023). "The relationship between CLDN5 expression and patient prognosis using a pan-cancer dataset was analyzed." (PMID 37286335, 2023). "Within BrM-cores (but not BrM-margins), cancer-adjacent endothelial cells exhibited lower claudin-5 expression compared with cancer-avoiding endothelial cells." (PMID 36725935, 2023). "Altogether, it indicates that the expression of CLDN5, CLDN11, CLDN2, CLDN7, and CLDN12 is associated with regulating the key cancer-associated pathways in the COAD and GSEA datasets." (PMID 37799140, 2023). "CLDN5 expression influenced DSS in the following seven cancer types: COAD, KIRP, LUSC, UVM, STAD, GBMLGG, and KIRC." (PMID 37286335, 2023).
cancer (continued). "This study contributes to the development of CLDN5-targeting therapeutic strategies by bringing attention to the use of CLDN5 as a possible prognostic biomarker in a variety of cancers in the context of immuno-oncology." (PMID 37286335, 2023). "In this report, the importance of CLDN5 in pan-cancer as a potential biomarker and a valuable immune filter has been analyzed." (PMID 37286335, 2023). "CLDN5 expression, enrichment analysis, pathway analysis, and correlation with cancer prognosis in the Cancer Genome Atlas (TCGA) and other public databases were investigated in this study." (PMID 37286335, 2023). "Claudin-5 is one of the main components of tight junctions for cancer cells to connect adjacent cells." (PMID 33004792, 2020). "For example, Slc2a1 (Glut1) was clustered together with Cldn5 (claudin 5) and Abcg2 (the breast cancer protein) in both cerebral structures, but it was clustered closely only with Abcc1 (multidrug resistance protein 1) in the hippocampus." (PMID 30298005, 2018). "Restoring and enhancing the expression of claudin-1 or stabilizing claudin-5 could potentially inhibit cancer cell invasion and metastasis." (PMID 39858080, 2025). "Briefly, myeloid cells (LYZ+), lymphocytes (CD3D+), osteoclasts (ACP5+), endothelial cells (CLDN5+), perivascular-like cells (PVL) (RGS5+TAGLNhigh), cancer-associated fibroblasts (CAFs) (TAGLNlowACTA2+) and proliferative cells (MKI67+) were identified in the study." (PMID 36596773, 2023). "Moreover, the frequency of claudin-5+ cancer-adjacent endothelial cells was lower in BrM-cores compared with BrM-margins, supporting a model of vascular co-option during BrM colonization that is initiated in regions of weakened endothelial junctions." (PMID 36725935, 2023). "The reason why expression of claudin-5 in many cancer is different is still a controversial issue." (PMID 27398181, 2016). "The cases positive to claudin-5 and claudin-7 were divided into 2 groups, the low expression group (cases with less than 50% of positive cancer cells) and the high expression group (cases with more than 50% of positive cancer cells) for clinicopathological correlation." (PMID 27398181, 2016). "This work suggests that Claudin-5 might be involved in cancer cell motility; in particular, it appears to be involved in the signalling pathway of N-WASP and ROCK." (PMID 22559840, 2012). "Moreover, claudin-5 plays a crucial role in various processes in vascular BMECs, such as motility, matrix adhesion, and angiogenic potential, which may impact cancer cell interactions with the blood vessels." (PMID 39858080, 2025). "Recent experiments have confirmed that HeLa cells reduce tight junction-related proteins ZO-1 and CLDN5 by activating the EV-endoplasmic reticulum stress process, thereby destroying the tight junctions of endothelial cells and breaking through the defense line leading to cancer metastasis." (PMID 39165926, 2024). "In vitro, cANGPTL4 interacts with integrin α5β1, VE-cadherin, and claudin-5 to disrupt endothelial cells and thus to increase vascular permeability: this could be how cancer cells expressing and secreting cANGPTL4 could disrupt and thus cross the blood-brain barrier." (PMID 32405335, 2020). "Cells exhibiting high expression of BCAN, GFAP, and EGFR were categorized as cancer cells, while endothelial cells displayed elevated levels of FLT1, CLDN5, and ABCG2." (PMID 41041071, 2025). "MMP1 facilitates cancer cell transit across the endothelium of the brain and increases BBB permeability by degrading the inter-endothelial junctions (claudin-5 and occludin)." (PMID 37190188, 2023). "In summary, the prevailing research suggests that CLDN5 is related to immune infiltration, MSI, TMB, and DNA methylation in various cancers, as well as the outcomes of cancer patients and immune infiltration across diverse cancers, particularly STAD." (PMID 37286335, 2023).
cancer (continued). "Taken together, SFN-Cys might cause microtubule disruption, regulate mitophagy and the expression of S100A4 and Claudin-5 inhibiting migration and invasion in GBM cells; the investigation of the underlying mechanisms will help us design brand-new, effective and safe drugs to treat invasive cancers." (PMID 33004792, 2020). "Additionally, a distinct correlation was observed between ADAR1 expression and the stromal cell marker CLDN5 in blood endothelial cells (BECs) and lymphatic endothelial cells (LECs), providing a refined perspective on ADAR1’s role across various cancer types." (PMID 40852728, 2025). "CLDN5 expression was studied in patients with stages I, II, III, and IV cancers, including the correlation between CLDN5 expression and clinicopathological features in various cancers." (PMID 37286335, 2023). "The abundance of genes related to vascular stability (CDH5, CLDN5, TIE1, JAM2, TEK) indicated that the group with a lower cholesterol score had higher vascular stability, while low vascular stability often promotes cancer growth." (PMID 38023262, 2023). "We examined whether miR-202-3p inhibitor or mimic could be transferred from cancer cells to the brain endothelium and whether miR-202-3p could directly target the 3’UTR of ZO-1, ß-catenin and claudin-5 mRNAs." (PMID 33002044, 2020). "Recently, it was shown that the overexpression of claudin-5 in hCMEC/D3 cells led to a reduction in the permeation of A549 cancer cells by approximately two-thirds, but did not lead to a noticeable improvement in electrical impedance." (PMID 32138745, 2020). "Treatment with 10 μM MK-2206, an Akt inhibitor widely used in the clinical trials for cancer indicated a significant decrease in the expression of phosphorylated Akt, Phosphorylated GSK-3α/β, claudin-5, ZO-1 and ZO-2 protein levels compared to DMSO-treated controls in HLECs." (PMID 29755115, 2018). "In addition, fibroblasts (n = 1 068) were identified by COL1A1 and FAP, endothelial cells (n = 2 561) were positive for RAMP2 and CLDN5 expression, smooth muscle cells (n = 1 100) were defined by TAGLN and CNN1, and epithelial/cancer cells (n = 319) were labeled by KRT14 and KRT17." (PMID 40360503, 2025). "Also, no comprehensive evaluation of the expression of CLDN5 and immunotherapy signatures through a pan-cancer analysis or immunoassay has been performed." (PMID 37286335, 2023). "The question therefore arises as to whether the absence of Claudin-5 in a cell alters levels of integrins and other adhesion-related proteins, thus changing the adhesion of the cancer cell when compared to the control." (PMID 22559840, 2012). "However, CLDN5 has not received considerable attention in pan-cancer research." (PMID 37286335, 2023). "The expression of CLIC2 and tight junction proteins is upregulated in non-cancer, compared with cancer cells, and CLIC2 regulates the formation of tight junction proteins such as claudin 1, claudin 5, zonula occludens-1, and occludin." (PMID 35205604, 2022).
neurological diseases (16 papers, 2015 to 2026). "Increased expression of claudin-5 has been associated with neuroprotective effects in neurological diseases." (PMID 41590739, 2026). "If these results are replicated and future studies support a mechanistic role for CLDN5, this could inform the development of novel therapeutic approaches for reducing risk for neurological disease among those with PTSD." (PMID 41358302, 2025). "Cldn5 is a major tight junction protein in brain and retinal vasculature, a reduction leads to a disruption of barrier function and is associated with many neurological diseases." (PMID 39585982, 2024). "Many neurological diseases associated with severe inflammatory responses by infiltrated neutrophils or activated microglia such as multiple sclerosis, stroke and traumatic brain injury markedly reduce CLDN-5 expression level (see our previous review)." (PMID 36978081, 2023). "Our results suggest that loss of endothelial miR-27a-3p could be a critical event contributing to loss of claudin-5 and occludin, and therefore barrier dysfunction in neurological diseases, and restoring its expression could be a potential therapeutic strategy to preserve the barrier integrity." (PMID 35025943, 2022). "Tight junction proteins such as ZO-1, occludin and claudin-5 have been shown to be reduced in experimental neurological disease models, which consequently compromised the integrity of the BBB." (PMID 26952102, 2016). "Alterations in Aβs, NFL, and GFAP may reflect, in part, the underlying role of CLDN5 in BBB disruption and neurological disease." (PMID 41358302, 2025). "Finally, we summarize recent reports about the dosage-dependent effect of CLDN-5 expression on the development of neurological diseases in mice and discuss what cellular supports for CLDN-5 regulation are compromised in the BBB in human diseases." (PMID 36978081, 2023). "In this review, we focus on selected neurological diseases that can be initiated by CLDN-5 decline." (PMID 36978081, 2023). "We examined Claudin 1, Claudin 3, Claudin 5, Occludin and ZO-1 in 31 ALS-CP samples compared to 15 non-neurologic disease controls." (PMID 32586411, 2020). "Cldn5−/− mice die within a day of birth, so that no neurological diseases can be assessed using the adult animal." (PMID 36978081, 2023). "Moreover, a close relationship between the diminished CLDN5 expression in BMVECs and the BBB breakdown has been reported in a range of human neurological disorders." (PMID 29212157, 2017).